PSLNR (prostate enriched lncRNA)
Synonyms: LA16c-83F12.6
Gene: Long non-coding RNA gene on chromosome 22 (15,741,297 to 15,779,680, forward strand). Ensembl gene ENSG00000225255.
Diseases named in the same sentence as PSLNR in open-access papers:
PSLNR is named in the same sentence as 1 disease in open-access papers, as found by Europe PMC text mining. Sharing a sentence is not in itself a finding about the gene and the disease.
prostate carcinoma (2 papers, 2020 to 2022). A carcinoma that arises from epithelial cells of the prostate gland.